IL21R (interleukin 21 receptor)
Diseases named in the same sentence as IL21R in open-access papers (continued):
Sharing a sentence is not in itself a finding about the gene and the disease.
benign breast tumours (1 paper, 2024). "As shown by RNA-sequencing data, the mRNA expression level of IL21R gene in BC was significantly higher than that in benign breast tumours (mean FPKM value: 0.23 and 1.15 for benign breast tumour and BC, respectively, p-value = 7.49E–04)." (PMID 38723244, 2024). "Compared to benign breast tumours, all five CpG sites in IL21R amplicon showed significantly decreased methylation levels in both ER-negative and ER-positive BC patients." (PMID 38723244, 2024). "The methylation of IL21R showed efficient discriminatory power to distinguish benign breast tumours from BC (area under curve (AUC) = 0.88), and especially from ER-negative BC (AUC = 0.95), PR-negative BC (AUC = 0.93) and triple-negative BC (AUC = 0.96)." (PMID 38723244, 2024). "The altered methylation of IL21R was semi-quantitatively validated in an independent study with 566 tissue samples (279 BC vs. 287 benign breast tumours) using mass spectrometry." (PMID 38723244, 2024). "Further analysis found that the methylation level of IL21R showed a more excellent ability to discriminate early-stage BC patients from patients with benign breast tumours (benign vs. stage 0 & I BC, AUC = 0.90, 95% CI: 0.87–0.93)." (PMID 38723244, 2024). "Our own data from RNA-sequencing further demonstrated that the mRNA expression level of IL21R gene in BC was significantly higher than that in benign breast tumours." (PMID 38723244, 2024). "In the present study, we focus on patients with BC and patients with benign breast tumours, and disclosed altered methylation and expression of IL21R gene in the tissue samples by 850K methylation beadchip array and RNA sequencing analysis." (PMID 38723244, 2024). "In addition, compared to benign breast tumours, the methylation levels of IL21R were significantly lower in BC patients with triple-negative, covariates adjusted ORs were more than 1.54 for per 10% reduction in methylation level of each CpG site." (PMID 38723244, 2024). "Taken together, IL21R methylation could efficiently distinguish patients with BC, especially triple-negative BC, from women with benign breast tumour, suggesting IL21R methylation as a potential biomarker for BC." (PMID 38723244, 2024). "We disclosed significant IL21R hypomethylation in patients with BC compared to women with benign breast tumours, and revealed the somatic change of DNA methylation could be a potential biomarker for molecular pathology of BC." (PMID 38723244, 2024). "Methylation levels of IL21R amplicon at all CpG sites were also reduced in both HER2-positive and HER2-negative BC compared with benign breast tumours, but were more significant in HER2-positive BC (all p-values ≤7.98E–07)." (PMID 38723244, 2024). "Next, we validated IL21R methylation differences between benign and malignant breast tumours in FFPE samples from 287 patients with benign breast tumour and 279 patients with BC." (PMID 38723244, 2024). "Subsequently, IL21R hypomethylation in BC was validated in an independent study with FFPE samples of 279 BC and 287 benign breast tumours using mass spectrometry." (PMID 38723244, 2024). "Based on a comprehensive analysis of differentially methylated and expressed genes in the fresh frozen tissue samples of 18 benign breast tumours and 11 early-stage BC (stage 0-IIA), we identified a CpG site cg04931655 located within the intron 1 of the IL21R gene." (PMID 38723244, 2024).
brain infarct (1 paper, 2022). "IL-21R-deficient mice have reduced collateral vascular connections and increased brain infarct volume, suggesting that IL-21R regulates collateral vascular anatomy and innate neuroprotection." (PMID 35173738, 2022).
celiac disease (1 paper, 2024). An autoimmune genetic disorder with an unknown pattern of inheritance that primarily affects the digestive tract. "We found, as in celiac disease, strong upregulation of IL-17 signaling and Th17 cell differentiation in EED including induction of IL21, IL6, IL17A IL17F, IL22, IFNG, IL21R, and IL2RA." (PMID 39300663, 2024).
chronic hepatitis B (1 paper, 2017). "Significantly elevated levels of expression of IL21 and IL21R was observed in the livers of PBC patients, compared with those of chronic hepatitis B (CHB) patients, autoimmune liver hepatitis (AIH) patients or healthy controls (HC)." (PMID 28425483, 2017).
Cirrhosis (1 paper, 2021). A chronic disorder of the liver in which liver tissue becomes scarred and is partially replaced by regenerative nodules and fibrotic tissue resulting in loss of liver function. "To examine B cell phenotypes in D-LC caused by HBV, we performed flow cytometry using a panel of 11 markers (CD19, CD10, CD38, IgD, CD21, CD27, CCR7, CXCR3, CXCR4, CXCR5, and IL-21R) and demonstrated the changes of B cell subsets for the first time in HBV-associated advanced cirrhosis." (PMID 34248941, 2021).
colorectal cancer (1 paper, 2024). A primary or metastatic malignant neoplasm that affects the colon or rectum. "In the future, histological staining will be performed on patients with ablated recurrent colorectal cancer liver metastases to determine the expression distribution of IL-21R, which provides a basis for MWA combined with IL-21 treatment." (PMID 38833177, 2024).
genital herpes (1 paper, 2013). Herpes simplex infection of the genitals, most commonly caused by the herpes simplex-2 virus. "As the IL-21R expression was increased in vaginal tissue early after HSV-2 infection and disease was more severe in IL-21R KO mice than in WT we concluded that the IL-21 - IL-21R network is important in the innate response to genital herpes in mice." (PMID 24358128, 2013).
helminth infections (1 paper, 2019). "Mice deficient for the IL-21R (Il21r−/−) showed reduced accumulation of immune subsets in the intestine, including lymphocytes, and reduced sizes and numbers of intestinal granuloma following helminth infections, suggesting a critical requirement of the IL-21/IL-21R axis for mounting TH2 responses." (PMID 31867283, 2019). "Mice deficient for a functional IL-21/IL-21R axis failed to elicit anti-helminth-specific IgG1 responses and subsequently were unable to clear helminth infection as compared with their wild-type counterparts." (PMID 31867283, 2019).
Hodgkins lymphoma (1 paper, 2019). A heterogeneous group of malignant lymphoid neoplasms of B-cell origin characterized histologically by the presence of Hodgkin and Reed-Sternberg (HRS) cells in the vast majority of cases. "Similarly, previous studies have shown that IL-21 attracts regulatory T-cells via up-regulation of macrophage inflammatory protein-3α and protects cells from apoptosis via activation of STAT3 signaling pathways in IL-21R+ Hodgkin lymphoma cells." (PMID 30728806, 2019). "However, studies have shown IL-21R is also expressed on non-immune cells such as fibroblasts, endothelial cells, keratinocytes, and Hodgkin lymphoma cells." (PMID 30728806, 2019).
hyper-IgM syndrome (1 paper, 2021). A primary immune deficiency disorder characterized by defective CD40 signaling; via B cells affecting class switch recombination (CSR) and somatic hypermutation. "Additionally, both CD40L (hyper-IgM syndrome) and IL-21R mutations develop PCP, and it is possible that these important ligand-receptor relationships are impaired in this model." (PMID 33491669, 2021).
immunotoxicity (1 paper, 2010). "We used two types of positive controls: rhIL21 stimulation for signal transduction through the therapeutic target IL21R, and in vitro cross-linked anti-CD28 for induction of cytokines associated with immunotoxicity." (PMID 20504348, 2010).
latent infection (1 paper, 2017). "The total absence of cytokine signaling in IL-21R KO mice further exacerbates CD8 T cell exhaustion leading to increased reactivation of latent infection in these animals." (PMID 29163509, 2017).
leishmaniasis (1 paper, 2020). Infectious disease that is transmitted through the bite of hematophagous female phlebotomine sand flies. "Altogether, the contribution of IL-21/IL-21R to leishmaniasis remains a conundrum with limited studies on gene-deficient and receptor-deficient experiments to validate a distinct role." (PMID 33415318, 2020). "In line with this, evidence suggests that IL-21/IL-21R signalling regulates antibody isotype switching especially IgG subclasses, IgG1 and IgA, the former associated with progression of leishmaniasis." (PMID 33415318, 2020).
leprosy (1 paper, 2016). Leprosy is a chronic infectious disease affecting primarily the skin and peripheral nervous system. "The second suggestive association rs34411505 on 16p12.1 locates between IL4R and IL21R whose expressions were both elevated in the leprosy patients." (PMID 27976721, 2016). "IL4R and IL21R both encode immunomodulatory cytokine that regulate adaptive immunity responses, which play important role in the leprosy development." (PMID 27976721, 2016).
leukemia (1 paper, 2024). A malignant (clonal) hematologic disorder, involving hematopoietic stem cells and characterized by the presence of primitive or atypical myeloid or lymphoid cells in the bone marrow and the blood. "In line with the findings obtained in Il21−/− AML mice, Il21R−/− AML mice had a lower expression of CD11b on bulk leukemia cells." (PMID 39536753, 2024). "To verify that the cellular processes and signaling cascades identified in Il21−/− AML mice are also modulated in Il21R−/− AML mice, we assessed CD11b expression on bulk leukemia cells as well as phosphorylation states of IKBα and p38-MAPK in L-GMPs from Il21R−/− and control Il21R+/−AML mice." (PMID 39536753, 2024).
liver cancer (1 paper, 2024). An epithelial or non-epithelial malignant neoplasm that arises from the liver. "In contrast to their conclusion, our study demonstrated that ablation of IL-21R impeded liver cancer development, particularly MASH-driven HCC, in two different mouse models of spontaneous MASH-driven HCC: the STAM model and the WD&High sugar solution&CCl4 model." (PMID 38720319, 2024).
lung adenocarcinoma (1 paper, 2022). A carcinoma that arises from the lung and is characterized by the presence of malignant glandular epithelial cells. "Recently, it was report that T follicular helper cells producing IL-21 play crucial roles in lung adenocarcinoma, because these cells were able to induce the effect function of tumor-infiltrating CD8 via IL-21/IL-21R signaling." (PMID 35514957, 2022).
lymphopenia (1 paper, 2008). Reduction in the number of lymphocytes. "Improper regulation of T cell homeostatic mechanisms, such as IL-21 inhibition of T cell survival, can result in decreased numbers of lymphocytes, or lymphopenia, as observed in both NOD and C57BL/6 mice compared to IL-21R KO animals of both strains." (PMID 18773086, 2008).
mantle cell lymphoma (1 paper, 2022). Mantle cell lymphoma is a rare form of malignant non-Hodgkin lymphoma affecting B lymphocytes in the lymph nodes in a region called the ``mantle zone''. "Upon further analysis of this published data set generated in the mantle cell lymphoma cell line Rec-1, we found a consensus RBPj site within intron 2 of the IL21r locus, which showed strong binding of RBPj and MAML, as well as γ-secretase inhibitor–sensitive (GSI-sensitive) Notch1 binding." (PMID 35349492, 2022).
metabolic syndrome (1 paper, 2016). A cluster of metabolic risk factors for CARDIOVASCULAR DISEASES and TYPE 2 DIABETES MELLITUS. "Hence, circulating IL-21R+ T cells might act as a novel biomarker allowing identification of patients with metabolic syndromes." (PMID 27095356, 2016).
multiple myeloma (1 paper, 2024). "Similarly, the vast majority of HSPCs (12/15) derived from the BM of these 15 patients with multiple myeloma 14 days after allogeneic stem cell transplantation did not express the IL-21R on the surface." (PMID 39536753, 2024).
myasthenia gravis (1 paper, 2025). Myasthenia gravis (MG) is a rare, clinically heterogeneous, autoimmune disorder of the neuromuscular junction characterized by fatigable weakness of voluntary muscles. "Following IL-21R–Fc intervention, the frequency of plasmablasts and AQP4-ab levels were significantly reduced, corroborating previous studies in NMOSD and myasthenia gravis." (PMID 41567208, 2025).
nephritis (1 paper, 2018). Inflammation of renal tissue. "Collectively, IL-21R deficiency abolished the autoimmune SLE-like nephritis and Sjögren’s syndrome diseases associated with Act1 deficiency." (PMID 30013031, 2018).
neuropathy (1 paper, 2024). A disorder affecting the nervous system that manifests with pain, tingling, numbness, and/or muscle weakness. "In “mix-and-match” adoptive transfer experiments, in which CD4+ and CD8+ T cells were either from IL-21R–sufficient or IL-21R-deficient NOD.AireGW/ mice, a modest delay in the development of neuropathy was noted when CD4+ T cells were IL-21R deficient." (PMID 39087473, 2024). "Genetic IL-21R deficiency completely protected against neuropathy development, demonstrating that IL-21 signaling was required for autoimmune pathogenesis." (PMID 39087473, 2024). "The experimental group treated with anti–IL-21R antibody showed a decreasing trend in the incidence of neuropathy, electromyography (EMG) abnormalities, and CD4+ T cell infiltration." (PMID 39087473, 2024). "Finally, we demonstrated that IL-21 receptor–KO (IL-21R–KO) mice were protected from neuropathy development and had decreased immune infiltration into peripheral nerves." (PMID 39087473, 2024). "Female NOD.AireGW/ mice with a heterozygous mutation in the IL-21R (NOD.AireGW/ IL-21RHet mice) developed neuropathy with the same onset and incidence as NOD.AireGW/ mice sufficient for the IL-21R (NOD.AireGW/ IL-21RWT)." (PMID 39087473, 2024).
pancreatic ductal adenocarcinoma (1 paper, 2024). An infiltrating adenocarcinoma that arises from the epithelial cells of the pancreas. "In contrast, IL21R was expressed in pancreatic tumour cell lines and in the tissues of pancreatic ductal adenocarcinoma (PDAC), but not in normal pancreatic tissues, indicating that IL21R gene might contribute to PDAC progression as an oncogene." (PMID 38723244, 2024).
parathyroid disease (1 paper, 2025). "Although classified as VUS, several candidate genes previously reported to be associated with parathyroid disease, including ITPR2, IL21R, MMP14, TWIST1 and ESR2 were identified in three patients with cancer-type tumors." (PMID 40434298, 2025).
pemphigus (1 paper, 2021). Pemphigus is a group of rare autoimmune diseases that cause blistering of the skin and mucous membranes (mouth, nose, throat, eyes, and genitals).This conditioncan occur at any age, but often strikes people in middle or older age. "While we noted increased mRNA expression of IL17 in only one canine pemphigus case (case 4), we did note increased IL21R." (PMID 34660634, 2021).
pneumonia (1 paper, 2013). An acute, acute and chronic, or chronic inflammation focally or diffusely affecting the lung parenchyma, caused by an infection in one or both of the lungs (by bacteria, viruses, fungi, or mycoplasma.). "Notably, in a model of acute lung infection, it was recently demonstrated that IL-21R−/− mice are protected from fatal lung immunopathology induced by pneumonia virus." (PMID 23696736, 2013).
prostatitis (1 paper, 2019). An infectious or non-infectious inflammatory process affecting the prostate gland. "Consistent with human BPH and our in vitro cell proliferation study, IL-21R was upregulated in the prostate of the LPS induced prostatitis and BPH rat model." (PMID 30728806, 2019). "Prostatic hyperplasia was observed with IL-21R upregulated in LPS induced prostatitis rats." (PMID 30728806, 2019). "BPH concomitant with prostatitis significantly upregulated the expression of IL-21R." (PMID 30728806, 2019).
pulmonary fibrosis (1 paper, 2023). Chronic progressive interstitial lung disorder characterized by the replacement of the lung tissue by connective tissue, leading to progressive dyspnea, respiratory failure, or right heart failure. "In addition, the expression of IL-21 receptor (IL-21R) is detected in infiltrating lymphocytes of human pulmonary fibrosis specimens, suggesting that IL-21-responsive lymphocytes might be related to the progression of pulmonary fibrosis." (PMID 37628716, 2023).
steatosis (1 paper, 2024). Increased lipid within the cytoplasm of cells. "Importantly, HCC patients with high IL-21R expression exhibited severe steatosis." (PMID 38720319, 2024).
Stroke (1 paper, 2022). Sudden impairment of blood flow to a part of the brain due to occlusion or rupture of an artery to the brain. "We also illustrate that neurons express IL-21R in the peri-infarct regions of both mice and human stroke tissue in vivo." (PMID 35624463, 2022). "Representative images and quantifications reveal that these NeuN+ IL-21R+ cells not only exist, but also have a higher prevalence in human stroke tissue versus control tissue." (PMID 35624463, 2022). "Recently, it was demonstrated that global deletion of IL-21R in mice is detrimental to stroke outcome in a different model (permanent MCAO)." (PMID 35624463, 2022). "To test whether these NeuN+ IL-21R+ cells exist in ischemic brain tissue in our human samples, we stained human stroke tissue in the peri-infarct regions and in human control tissue." (PMID 35624463, 2022). "Moreover, revealing what regulates IL-21R expression on neurons following hypoxic conditions and understanding the role of the JAK/STAT pathway in stroke, can help elucidate why certain stroke patients may be susceptible to immune-mediated neuronal death." (PMID 35624463, 2022).
synovitis (1 paper, 2016). Inflammation of a synovial membrane. "Histological examination showed no cellular infiltrates in the joints of Il21r KO mice, while massive synovitis with cartilage and bone destruction was detected in WT mice." (PMID 27535236, 2016).